ID3 (inhibitor of DNA binding 3)
Diseases named in the same sentence as ID3 in open-access papers (continued):
Sharing a sentence is not in itself a finding about the gene and the disease.
Stroke (3 papers, 2019 to 2023). Sudden impairment of blood flow to a part of the brain due to occlusion or rupture of an artery to the brain. "The diagnostic robustness of the identified 10 candidate genes (ID3 is one of 10 candidate genes) in an independent patient population, and further suggest that it is temporally stable over the first 24 hr of stroke pathology (O'Connell, Chantler, & Barr, 2017)." (PMID 31168961, 2019). "A predictive model with 89.6% accuracy was identified using 6 network-central and differentially expressed genes (ID3, MBTPS1, NOG, SFXN2, BMX, SLC22A1), characterized by large differences in association network connectivity between stroke and control samples." (PMID 31391037, 2019). "Notably, ID3 was found to be time-stable in the early 24 hours of stroke in previous study, further highlighting the importance of this gene in the early diagnosis of the disease." (PMID 38112574, 2023). "Furthermore, the association of ID3 and SLC22A4 with immune cells may be a new direction for post-stroke immunotherapy." (PMID 38112574, 2023). "Analysis of the discovery dataset (GSE58294, GSE22255) showed a significant decrease in ID3 expression and a significant upregulation of SLC22A4 expression in stroke patient samples compared with controls." (PMID 38112574, 2023). "The mRNAs of ID3, MBTPS1, NOG, and SFXN2 have lower concentrations (are down-regulated) in the stroke samples (log FC = − 0.915, − 0.356, − 0.752, − 0.301, respectively) while BMX and SLC22A11 are up-regulated (log FC = 0.456, 0.365) in the stroke patients." (PMID 31391037, 2019). "While most of the 6 network central genes also have significantly different expression levels between stroke and control, with the exception of ID3, they are not necessarily among the set of most highly dysregulated genes." (PMID 31391037, 2019).
acute leukemia (2 papers, 2017 to 2022). A clonal (malignant) hematopoietic disorder with an acute onset, affecting the bone marrow and the peripheral blood. "Id2 and Id3 show different expression patterns and subcellular localization in acute leukemia subtypes: for example, AML is characterized by higher Id2 and Id3 expression than acute lymphoblastic leukemia (ALL)." (PMID 28122577, 2017).
acute lymphoblastic leukemia (2 papers, 2017 to 2025). Leukemia with an acute onset, characterized by the presence of lymphoblasts in the bone marrow and the peripheral blood. "In adult Hispanic B-cell acute lymphoblastic leukemia (B-ALL), high JCHAIN expression-part of a 3-gene signature with ID1 and ID3-predicts poor induction therapy response and shortened survival, driven by NF-κB pathway hyperactivation." (PMID 41153653, 2025).
acute myeloid leukemia (2 papers, 2017 to 2022). Acute myeloid leukemia (AML) is a group of neoplasms arising from precursor cells committed to the myeloid cell-line differentiation. "Overexpressed Id1 or Id3 are able to immortalize growth factor-dependent hematopoietic progenitors resulting in cells with an acute myeloid leukemia (AML)-like morphology and decreased p15INK, p16INK4, p19ARF and p21Cip1 in vitro." (PMID 28122577, 2017).
autoimmune disease (2 papers, 2014 to 2021). A disorder resulting from loss of function or tissue destruction of an organ or multiple organs, arising from humoral or cellular immune responses of the individual to their own tissue constituents. "Id3-deficient mice develop an autoimmune disease similar to human SS, but Id3 has been shown to be elevated in RA synovium and correlates with the SLEDAI in SLE." (PMID 33920997, 2021).
bladder cancer (2 papers, 2022 to 2025). "This transition leads to the downstream activation of regulated target genes, including ABCB1 and ID3, driving drug resistance in bladder cancer." (PMID 35406487, 2022). "MeRIP‐qPCR further revealed abundant m6A modifications on ID3 mRNA in bladder cancer cell." (PMID 40112217, 2025). "Meanwhile, by analyzing the MeRIP‐seq results of bladder cancer in GEO datasets (GSE231836), we found an obvious m6A peak in the 3′UTR region of ID3 mRNA, which aligned with the sites predicted by SRAMP software." (PMID 40112217, 2025).
chronic lymphocytic leukemia (2 papers, 2015 to 2017). "Our study provides evidence for a pro-survival function of the ID2/ID3 proteins in chronic lymphocytic leukemia cells and also highlights these proteins as potential determinants of the pathobiology of this disorder." (PMID 25644253, 2015).
diabetic nephropathy (2 papers, 2023). "Less is known at present about the specific role of ID3 in the context of diabetic nephropathy, but our findings suggest that it may also play an important role in its pathogenesis." (PMID 37863933, 2023).
endothelial dysfunction (2 papers, 2014 to 2024). In vascular diseases, endothelial dysfunction is a systemic pathological state of the endothelium (the inner lining of blood vessels) and can be broadly defined as an imbalance between vasodilating and vasoconstricting substances produced by (or acting on) the endothelium. "Overall, the impact of ID3 on cardiac illnesses has been thoroughly investigated using different models, uncovering its pivotal role in vascular remodeling, endothelial dysfunction, and regulation of adipose tissue." (PMID 39846697, 2024). "In endothelial dysfunction, ID3 influences VEGF signaling, boosting endothelial cell proliferation and contributing to microvascular lesion formation." (PMID 39846697, 2024). "The interaction between EED exposure and ID3 signaling involves a network of pathways driving oxidative stress, inflammation, endothelial dysfunction, and vascular remodeling." (PMID 39846697, 2024). "Here, we present evidence for how PCB-induced ROS may contribute to the development of a neovascular phenotype with the aim of elucidating the role of environmental toxicants in endothelial dysfunction with a specific focus on the inhibitor of differentiation protein ID3." (PMID 25090023, 2014).
esophageal cancer (2 papers, 2020 to 2025). A primary or metastatic malignant neoplasm involving the esophagus. "Patients with poorly differentiated esophageal cancer tended to have the highest Id3 expression level." (PMID 32760207, 2020).
Insulin resistance (2 papers, 2017 to 2025). Increased resistance towards insulin, that is, diminished effectiveness of insulin in reducing blood glucose levels. "Besides inflammation, ID3 may contribute to other risk factors of MetS such as angiogenesis, adipose tissue, blood glucose levels, and insulin resistance." (PMID 28785583, 2017). "ID3 furthermore plays a role in blood glucose, which if dysregulated can lead to insulin resistance." (PMID 28785583, 2017).
lung fibrosis (2 papers, 2014 to 2026). "Lung-specific inhibition of ID1/ID3 using adeno-associated viruses expressing short hairpins targeting ID1 and ID3 also reversed pulmonary fibrosis in mice." (PMID 42094605, 2026). "Pharmacological inhibition of ID1/ID3 decreased HLF proliferation, migration and differentiation in vitro and attenuated pulmonary fibrosis in vivo." (PMID 42094605, 2026).
metastatic disease (2 papers, 2021 to 2022). "In metastatic tumor cells, ID1 and ID3 facilitate the mesenchymal-to-epithelial conversion required for macro-metastatic disease progression, likely through antagonism of the bHLH protein Twist47." (PMID 34031428, 2021).
myopia (2 papers, 2023 to 2025). "Of note, recent studies using the lens-induced guinea pig myopia model also reported Id3 gene expression to be downregulated in RPE after both 1 and 7 days of negative lens treatment." (PMID 41369372, 2025). "As reported in our previous RNA sequencing study, Id3 gene expression was found to be downregulated across the CL wearing (myopia-inducing) period, i.e., after both one day and one week of CL wear, and consistent with the pattern of downregulation for Bmp2." (PMID 37759773, 2023). "In this study, we examined three gene expression changes in Bmp2, Id3, and Nog in RPE during myopia induction and subsequent recovery from myopia." (PMID 37759773, 2023). "Overall, there appears to be a tight, albeit inverse relationship between the directions of AL and BMP2 gene expression changes, with ID3 gene expression changes mirroring BMP2 gene expression changes during myopia induction but not during recovery from the same treatment." (PMID 37759773, 2023).
oral squamous cell carcinoma (2 papers, 2020 to 2021). "The oral squamous cell carcinoma cell HSC2, when exposed to milk, increased ID1 and ID3 genes but failed to increase IL11 (data not shown)." (PMID 34789212, 2021).
Rett syndrome (2 papers, 2010 to 2020). A severe neurodevelopmental disorder affecting the central nervous system.
rheumatoid arthritis (2 papers, 2005 to 2017). A chronic, systemic autoimmune disorder characterized by inflammation in the synovial membranes and articular surfaces. "The upregulation of ID1 and ID3 genes has been reported in patients with rheumatoid arthritis (RA)." (PMID 28785583, 2017). "Moreover, BMP-6 has been suggested to play a role in rheumatoid arthritis (RA) and elevated levels of Id1 and Id3 have been found in the synovia of RA-patients." (PMID 15877825, 2005).
T-Cell Lymphomas (2 papers, 2015 to 2021). "Taken together, these data point to a regulatory circuitry that maintains thymocyte quiescence and provide a mechanism involving c-myc and p19Arf that underpins the development of T-cell lymphoma in Id2- and Id3-deficient T cells." (PMID 25691468, 2015). "Likewise, we found that Id2- and Id3-depleted murine T-cell lymphomas expressed relatively high levels of c-Myc expression." (PMID 25691468, 2015).
thyroid cancer (2 papers, 2014 to 2024). "For example, ID1 regulates growth and differentiation in thyroid cancer cells, and ID3 was also identified as an early response protein and tumor marker for thyroid carcinomas." (PMID 24718460, 2014). "However, the expression levels of ID1, ID3, and ID4 were downregulated in thyroid cancer." (PMID 38195969, 2024).
triple-negative breast carcinoma (2 papers, 2020 to 2021). An invasive breast carcinoma which is negative for expression of estrogen receptor (ER), progesterone receptor (PR), and human epidermal growth factor receptor 2 (HER2). "A decrease in ID1 and ID3 protein levels was also observed in a PDX cell line (IBT) generated from a patient with triple-negative breast cancer (TNBC)." (PMID 34031428, 2021). "The basic helix-loop-helix (bHLH) transcription factors inhibitor of differentiation 1 (Id1) and inhibitor of differentiation 3 (Id3) (referred to as Id) have an important role in maintaining the cancer stem cell (CSC) phenotype in the triple-negative breast cancer (TNBC) subtype." (PMID 32911668, 2020).
tuberculosis (2 papers, 2021 to 2022). A chronic, recurrent infection caused by the bacterium Mycobacterium tuberculosis. "Overall, our study suggests that IL-7 and transcriptional factors Id3 and Bcl6 help the TB subunit vaccine to induce long-term immune memory, which contributes to providing immune protection against M. tuberculosis infection." (PMID 33562631, 2021). "Therefore, IL-7 and transcription factors Id3 and Bcl6 could help the TB subunit vaccine to induce long-term immune memory, which would provide long-term immune protection against M. tuberculosis infection." (PMID 33562631, 2021).
acute promyelocytic leukemia (1 paper, 2022). An aggressive form of acute myeloid leukemia (AML), characterized by arrest of leukocyte differentiation at the promyelocyte stage, due to a specific chromosomal translocation t(15;17) in myeloid cells. "Studies have shown that RARα antagonizes E protein activity by inducing transcription of ID1 and ID2 in human acute promyelocytic leukemia cells treated with all-trans-retinoic acid and ID1 and ID3 gene expression in normal human keratinocytes." (PMID 35503250, 2022).
age (1 paper, 2024). A temporal measurement of the time period elapsed since an identifiable point in the life cycle of an organism. "The interplay between NFκB, PDGF-BB, LY6E, ID3, PTP4A1, and FOS in age-related vascular endothelial dysfunction and related pathologies underscores the complexity of molecular mechanisms governing vascular health." (PMID 38674087, 2024).
ameloblastoma (1 paper, 2020). The most common odontogenic tumor, arising from the epithelial component of the embryonic tooth and usually affecting the molar-ramus region of the mandible or maxilla. "Interestingly, we found that TGF‐β signaling‐related genes including transforming growth factor beta 3 (TGFB3), snail family transcriptional repressor 1 (SNAI1), and inhibitor of DNA binding 3 (ID3) were significantly activated in ameloblastoma tumors." (PMID 32096304, 2020).
anemia (1 paper, 2016). A reduction in the number of red blood cells, the amount of hemoglobin, and/or the volume of packed red blood cells. "Disruption of Id1 and Id3 genes in Id cDKOs led to the development of multiple hematopoietic disturbances including anemia." (PMID 27128622, 2016). "Our findings reveal that Id3 KO mice do not develop anemia, although a small fraction progress to develop splenomegaly by 10 months." (PMID 27128622, 2016).
angiomyolipoma (1 paper, 2017). A neoplasm with perivascular epithelioid cell differentiation often associated with tuberous sclerosis. "We used a genetic strategy for cell-specific depletion of Tsc1 in the mouse embryo NT because expression of ID1 and ID3 was suppressed in angiomyolipoma cells in N-medium, Id proteins as well as high level of Hes1 prevent neurogenesis in NT50, 51, and Id3 and Hes1 are regulated by Notch154." (PMID 29184052, 2017).
asthma (1 paper, 2021). "In our study, EP300, ID1, ID3, SMAD2, and SMAD5 were DC with a loss of connectivity, whereas SMAD7 exhibited a network connectivity gain due to asthma." (PMID 34257337, 2021).
Autoimmunity (1 paper, 2019). The occurrence of an immune reaction against the organism's own cells or tissues. "Id2 and Id3 are essential for Treg maintenance, and Treg-specific Id2/Id3 double knockout mice are lethal due to multi-organ autoimmunity and show increased Tfr number." (PMID 31434282, 2019).
biliary tract cancer (1 paper, 2023). "And similar to ID1 and ID3 proteins, ID2 is overexpressed in biliary tract cancer." (PMID 39130146, 2023).
bladder tumors (1 paper, 2022). "Regarding the ID family genes, the expression of ID2, ID3, and ID4 but not ID1 was significantly lower in bladder tumors than in normal urothelium." (PMID 35729325, 2022).
Cachexia (1 paper, 2018). Severe weight loss, wasting of muscle, loss of appetite, and general debility related to a chronic disease. "While these findings would suggest that ID3 is the dominant ID protein in myoblasts under normal physiological conditions, in disease states where C/EBPβ expression is induced in myoblasts, for example cachexia, both Id1 and Id3 upregulation are likely to contribute." (PMID 30413755, 2018).
Cirrhosis (1 paper, 2012). A chronic disorder of the liver in which liver tissue becomes scarred and is partially replaced by regenerative nodules and fibrotic tissue resulting in loss of liver function. "BMP2, BMPR1A, FGF7, FGFR2 and ID3 were more highly expressed in cirrhosis than HCC, while the BMP inhibitors were more highly expressed in tumors." (PMID 23667740, 2012).
colon adenocarcinoma (1 paper, 2021). "In low-grade glioma (LGG), thymoma (THYM), diffuse large B-cell lymphoma (DLBC) and colon adenocarcinoma (COAD), we identified groups with low ID3 expression which also show a low enrichment score of HR-related pathways." (PMID 34718742, 2021).
congenital heart disease (1 paper, 2023). A heart disease that is present at birth. "Indeed, ID proteins are among the most highly regulated downstream targets of BMP/Smad signaling, and their importance was recently reported, as the loss of ID1 and ID3 expression associated with BMPR2 mutations contributed to cardiomyocyte dysfunction in patients with congenital heart disease." (PMID 37298503, 2023).
cutaneous melanoma (1 paper, 2018). A primary melanoma arising from atypical melanocytes in the skin. "Importantly, we found that coordinate expression of Id1 or Id3 with HA synthases HAS2, HAS3, and CD44 is associated with reduced overall survival of cutaneous melanoma patients." (PMID 30297743, 2018). "Consistently, coordinate expression of Id1 or Id3 with HAS2, HAS3 or CD44 significantly correlated with reduced survival of cutaneous melanoma patients." (PMID 30297743, 2018).
developmental delay (1 paper, 2021). "This case shows potential overlap of clinical presentation due to multiple deleterious variants, of which the LMX1A variant is the strongest etiology of inner ear abnormalities in this patient while the ZFHX4 or ARHGAP4 variants may explain ID3’s developmental delay." (PMID 33924653, 2021).
dilated cardiomyopathy (1 paper, 2017). Cardiomyopathy which is characterized by dilation and contractile dysfunction of the left and right ventricles. "To bypass embryonic lethality we used Tie2CRE-mediated recombination to conditionally delete Id1 against global Id3 ablation (Id cDKOs), which develops adult-onset dilated cardiomyopathy." (PMID 28596553, 2017).
familial cancer (1 paper, 2022). "The majority of germline alterations were unknown or benign, with the exception of one alteration each in familial cancer genes MUTYH, CHEK2, and FANCL, as well as one germline alteration in ID3." (PMID 36232827, 2022).
hyperlipidemia (1 paper, 2017). "ID3 expression is increased by hyperlipidemia and oxidized LDL." (PMID 28785583, 2017).
inflammatory bowel disease (1 paper, 2015). A spectrum of small and large bowel inflammatory diseases of unknown etiology.
insomnia (1 paper, 2021). A sleep disorder characterized by difficulty in falling asleep and/or remaining asleep. "Except for the reported findings, we found one set of genes including ID1, ID2, and ID3 was significantly enriched in biological processes of the circadian rhythm and speculated that insomnia in some PCOS patients may due to the abnormal expression of these genes." (PMID 34113617, 2021).
insulinoma (1 paper, 2023). "Both ID1 and ID3 were upregulated by high glucose in cultured human pancreatic islets or insulinoma cells." (PMID 37863933, 2023).
Intellectual disability (1 paper, 2019).
invasive ductal carcinoma (1 paper, 2022). "Expression of ID1 and ID3 was increased in human invasive lobular carcinoma compared with invasive ductal carcinoma, associated with poor prognosis uniquely in patients with invasive lobular carcinoma and correlated with the upregulation of angiogenesis and matrisome-related genes." (PMID 36443709, 2022).
ischemia (1 paper, 2015). A hypoperfusion of the BLOOD through an organ or tissue caused by a PATHOLOGIC CONSTRICTION or obstruction of its BLOOD VESSELS, or an absence of BLOOD CIRCULATION. "No ID2+ or ID3+ cells were detected in the hippocampus proper (CA1-CA3) of both the sham-operated and the ischemia groups (data not shown)." (PMID 25503067, 2015).